RN7SL657P (RNA, 7SL, cytoplasmic 657, pseudogene)
Gene: Miscellaneous RNA gene on chromosome 1 (1,405,460 to 1,405,752, reverse strand). Ensembl gene ENSG00000264293.
Homologues: Orthologues: chimpanzee Metazoa_SRP (97% identical), macaque Metazoa_SRP (90% identical), dog Metazoa_SRP (72% identical). Paralogues in human: RN7SL1 (82% identical), RN7SL3 (82% identical), RN7SL2 (81% identical), RN7SL398P (80% identical), RN7SL296P (79% identical), RN7SL220P (78% identical), RN7SL408P (78% identical), RN7SL357P (78% identical), RN7SL804P (78% identical), RN7SL856P (78% identical), RN7SL14P (77% identical), RN7SL478P (77% identical), and 705 more.